INS (insulin)
Diseases named in the same sentence as INS in open-access papers (continued):
Sharing a sentence is not in itself a finding about the gene and the disease.
type 2 diabetes (continued). "Given the heterogeneous and progressive nature of type 2 diabetes, we evaluated PAK1 regulation of insulin biogenesis-related genes under baseline conditions and performed RNA-seq analysis using PAK1-overexpressing ND human islets." (PMID 39404845, 2025). "While the study focused on the rs5435 variant of the SLC2A4 gene, it did not investigate other genetic variants involved in insulin signaling or glucose metabolism, which may also contribute to type 2 diabetes (T2D) risk through additive or interactive effects." (PMID 40854653, 2025). "GAS5 levels are markedly lower in serum samples from individuals diagnosed with type 2 diabetes mellitus (T2DM) and it affects insulin signaling and glucose uptake by binding to UPF1 and regulating insulin receptor expression." (PMID 40563948, 2025). "Type 2 diabetes advances faster when islet amyloid polypeptide (IAPP) builds up in the body because it damages beta cells and makes insulin resistance worse." (PMID 40225541, 2025). "The integration of advanced technologies, such as basal insulin therapy (PwT2D-BI) and continuous glucose monitoring (CGM), has shown significant promise in improving glycemic control for individuals with type 2 diabetes (T2D)." (PMID 40391004, 2025). "It has been shown that the administration of Z. officinale powder in individuals newly diagnosed with type-2 diabetes enhanced HDL, β-cell function index, and insulin sensitivity index." (PMID 40343290, 2025). "In the context of type 2 diabetes, AMPK activation improves insulin sensitivity, enhances glucose uptake in skeletal muscles, and reduces hepatic glucose production, thereby contributing to better glycemic control." (PMID 40563920, 2025). "Several patients were also on insulin, sulfonylureas, dipeptidyl peptidase 4 (DPP-4) inhibitors, and SGLT2 inhibitors, reflecting the progressive and multifaceted treatment needs of type 2 diabetes." (PMID 41018312, 2025). "In preclinical models of type 2 diabetes and NAFLD, MPC inhibitors have shown promise in enhancing insulin sensitivity, reducing hepatic steatosis, and attenuating inflammatory responses." (PMID 40001526, 2025). "A study that investigated the effects of insulin and GLP-1RAs (exenatide and dulaglutide) on BMD over a 52-week duration gathered 70 individuals with type 2 diabetes." (PMID 40708853, 2025). "Several risk factors were less favourable in the controls with a prior obesity diagnosis, including higher concentrations of fasting blood glucose, serum insulin, HOMA-IR and prevalence of type 2 diabetes, and worse self-rated health status." (PMID 40353980, 2025). "The authors determined the levels of blood glucose and insulin in streptozotocin (STZ)-induced type 1 diabetic mice and tetroxidine-induced type 2 diabetic mice after treatment with total flavonoids." (PMID 40276535, 2025). "This cohort study compares the risks of developing different hematologic cancers in patients with type 2 diabetes treated with glucagon-like peptide–1 receptor agonists (GLP-1RAs) compared with metformin and insulin." (PMID 40048168, 2025). "This study aimed to develop a non‐insulin version of the DEPS‐R and evaluate its screening performance for BED in people with type 1 and type 2 diabetes." (PMID 40440439, 2025). "As an incretin hormone, GLP-1 plays a fundamental role in glucose homeostasis by stimulating glucose-dependent insulin secretion from pancreatic beta-cells and inhibiting glucagon release, which is the primary mechanism by which GLP-1RAs treat type 2 diabetes." (PMID 41303457, 2025). "Decreases hepatic glucose production, lowers blood glucose and insulin levels, improves glucose tolerance, inhibits gluconeogenesis, and activates AMPK signaling, potentially beneficial for managing type 2 diabetes." (PMID 39963239, 2025).
type 2 diabetes (continued). "Furthermore, the stronger impact of MET on glucose metabolism compared to EMPA in our study may be attributed to MET's direct effects on insulin sensitivity, a mechanism that may be more relevant in the HFpEF model, which shares metabolic abnormalities with type 2 diabetes." (PMID 40364820, 2025). "Type 2 diabetes mellitus (T2DM) is a progressive metabolic disorder characterized by insulin resistance, impaired insulin secretion,and chronic hyperglycemia." (PMID 41466638, 2025). "Type 2 diabetes mellitus(T2DM) manifests as elevated blood glucose levels in patients, stemming from agradual reduction in insulin secretion by β-cells amidst insulinresistance." (PMID 40160590, 2025). "Overall in Type 2 diabetes patients participating in the ONWARDS 1, 2, 3, and 5 trial, the effect of insulin icodec showed a significantly greater A1C reduction from baseline compared to insulin degludec, glargine U100, and glargine U300." (PMID 40156735, 2025). "Glucagon-like peptide-1 (GLP-1) receptor agonists, initially developed for type 2 diabetes, have shown promise in managing GDM by improving glycemic control, enhancing insulin sensitivity, and assisting in weight management." (PMID 41054173, 2025). "A Spearman correlation analysis showed 3110045C21Rik and Ddr2 expression occur together in type 2 diabetes mellitus (T2DM) patients, which indicates 3110045C21Rik regulates insulin-signaling mechanisms." (PMID 40649811, 2025). "A case is presented of a 67-year-old female patient with a known diagnosis of type 2 diabetes mellitus, under metabolic control with 40 units of neutral protamine Hagedorn (NPH) insulin in the morning." (PMID 40941535, 2025). "Obesity and type 2 diabetes mellitus (T2DM) are among the most pressing global public health challenges of the 21st century, and are characterized by profound disturbances in systemic lipid metabolism and insulin action." (PMID 41002965, 2025). "The ONWARDS 1–5 Phase 3a randomised controlled trials compared the efficacy and safety of once-weekly basal icodec vs once-daily basal insulin in insulin-naive (ONWARDS 1, 3 and 5) and insulin-experienced (ONWARDS 2 and 4) adults with type 2 diabetes." (PMID 40186685, 2025). "Additionally, experiments have shown that curcumin can ameliorate glucose and lipid metabolism disorders, increase insulin sensitivity, and improve insulin resistance in animal models of type 2 diabetes mellitus (T2DM)." (PMID 40166470, 2025). "TNF-α, in particular, impairs insulin signaling by promoting serine phosphorylation of IRS-1, while IL-1β exacerbates pancreatic β-cell dysfunction and contributes to the development of type 2 diabetes." (PMID 40867531, 2025). "We accessed a list of 59 genes associated with glucose infusion rate of skeletal muscle (i.e. insulin sensitivity) and/or IMAT in the elderly with obesity and type II diabetes mellitus." (PMID 38099335, 2025). "Type 2 diabetes mellitus (T2DM) is a chronic metabolic disorder marked by persistent hyperglycemia due to insulin resistance and insufficient insulin secretion." (PMID 40608828, 2025). "Type 2 diabetes mellitus (T2DM) is a condition characterized by insulin resistance, inadequate pancreatic insulin secretion, and dysregulated glucagon secretion." (PMID 40012909, 2025). "Similar results have been reported in the ‘Restoring Insulin Secretion (RISE) Study’ and ‘Treatment Options for Type 2 Diabetes in Adolescents and Youth (TODAY) Study’." (PMID 41141343, 2025). "We observed ethnic differences in IPL, whereby BA men with type 2 diabetes exhibited lower IPL compared with WE men; this occurred alongside greater total insulin secretion in response to both the mixed-meal and the hyperglycaemic clamp." (PMID 40768046, 2025). "Type 2 Diabetes Mellitus (T2DM) arises from increased resistance to insulin action." (PMID 40566588, 2025).
type 2 diabetes (continued). "Type 2 diabetes mellitus (T2DM) is a chronic metabolic disorder characterized by persistent hyperglycemia due to insulin resistance, impaired insulin secretion, or both." (PMID 41300937, 2025). "In light of these properties and its GLP‐1 activity in regulating insulin secretion, in 2005, exendin‐4 (marketed as exenatide) became the first peptide approved by the FDA for the treatment of type II diabetes." (PMID 39720890, 2025). "Insulin strongly reduced plasma BCAA levels by 44–53% in the lean and obese groups (all p<0.001) and by 29% in the type 2 diabetes group (p<0.001)." (PMID 40404819, 2025). "Another significant study in this field, the First Basal Insulin Evaluation (FINE) Asia study, was a multinational, prospective, observational approach to assess BI’s efficacy in patients with uncontrolled type 2 diabetes (HbA1c ≥8%)." (PMID 39694849, 2025). "Studies in patients with metabolic syndrome and type 2 diabetes mellitus demonstrate improvements following DHA supplementation, including enhanced lipid profiles, reduced blood pressure, and improved insulin sensitivity." (PMID 40807354, 2025). "Circulating levels of TNFα are increased in obesity, type II diabetes and fatty liver disease; TNF clearly impairs insulin signaling." (PMID 40766326, 2025). "A case of a 55-year-old male patient with a prior diagnosis of type 2 diabetes and poor metabolic control who uses NPH insulin and crystalline insulin." (PMID 40941535, 2025). "In insulin-resistant states, such as type 2 diabetes and NAFLD, hepatic overproduction of SeP exacerbates metabolic dysfunction by inhibiting insulin action in peripheral tissues." (PMID 41341131, 2025). "In type 2 diabetes, however, this complex mechanism is disrupted, primarily due to impaired GLUT4 translocation and abnormal insulin signal transduction." (PMID 40807271, 2025). "Type 2 diabetes mellitus (T2DM) is a chronic, progressive metabolic disorder characterised by insulin resistance, impaired insulin secretion, and persistent hyperglycemia." (PMID 41211260, 2025). "Many studies have shown that in type 2 diabetes, FOXO1 is involved in glucose and lipid metabolism, insulin resistance, and β-cell proliferation, differentiation, and apoptosis, making it an important target for potential therapeutic intervention." (PMID 40951426, 2025). "Type 2 diabetes mellitus (T2DM) is characterized by a chronic hyperglycemic state, which is often attributed to insulin resistance in peripheral tissues, such as skeletal muscles and adipose tissue." (PMID 40650008, 2025). "Effect of gallic acid and vitamin C on the blood glucose, serum insulin, homeostatic model assessment of insulin resistance, and pancreatic β‐cell function in fructose/STZ‐induced type 2 diabetic rats." (PMID 40735405, 2025). "Type 2 diabetes mellitus (T2DM) is a chronic metabolic disease characterized by hyperglycemia due to impaired pancreatic β-cell function and insulin resistance." (PMID 40003935, 2025). "The researchers compared preadipocytes from insulin-resistant (IR), type 2 diabetes mellitus (T2DM), and insulin-sensitive (IS) individuals and found significant differences in their adipogenic capacity." (PMID 40332335, 2025). "In particular, knowledge of the availability of automated insulin delivery (AID) systems for managing type 1 diabetes in pregnancy, and of glucose continuous monitoring (CGM) systems for gestational and type 2 diabetes, needs to be increased." (PMID 41212214, 2025). "In mouse models of type 2 diabetes, nine weeks of PPH reduced fasting blood glucose by ~30%, improved glucose tolerance, enhanced insulin signaling, and reduced inflammation." (PMID 41305580, 2025). "Type 2 diabetes mellitus (T2DM) is a complex and progressive disease characterized by chronic hyperglycemia resulting from insulin resistance, impaired insulin secretion, and increased gluconeogenesis." (PMID 40988753, 2025).
type 2 diabetes (continued). "A Swedish study that defined metabolic syndrome with obesity, type 2 diabetes, HDL‐cholesterol, treated hypertension and fasting insulin saw that patients with metabolic syndrome had greater PV than patients without metabolic syndrome (49.0 ml vs 28.5 ml)." (PMID 40955380, 2025). "In older adults with type 2 diabetes (T2DM), tight glycaemic control (HbA1c < 7%) can result in more harm than benefit, especially when using insulin or sulfonylureas." (PMID 39846108, 2024). "Type 2 diabetes (T2DM) is a chronic illness normally occurring in adults, especially the elderly, characterized by an impaired response to insulin (insulin resistance) leading to impaired glucose control and thus chronic hyperglycemia." (PMID 39000211, 2024). "Fasting glucose and insulin levels were similarly increased in women under 40 years old with DOR and POI, but the prevalence of overt type 2 diabetes was very low in both groups." (PMID 39274315, 2024). "Endogenous hyperinsulinemia, common in type 2 Diabetes due to reduced insulin sensitivity, activates insulin receptors, IGF-1 receptors, and hybrid insulin/IGF-1 receptors, promoting cancer cell proliferation, survival, and metastasis." (PMID 38831236, 2024). "The results showed that insulin-loaded nanoparticles could be stable in gastric juice and effectively released in intestinal fluid when simulated digestion in vitro, as our expectations, and it could alleviate type 2 diabetic mice by reducing fasting blood glucose values." (PMID 39458652, 2024). "Examples of search terms included: "Type 2 Diabetes AND SGLT2 inhibitors AND DPP-4 inhibitors", "Metformin AND Insulin AND glycemic control", and "combination therapy AND long-term outcomes"." (PMID 39723311, 2024). "Previous meta-analyses focused on their use only in patients with type 2 diabetes and demonstrated that icodec and BIF provided effective and safe blood glucose control comparable to once-daily insulin." (PMID 39629047, 2024). "These actions improve insulin sensitivity and reduce hepatic lipid accumulation, thereby protecting against nonalcoholic fatty liver disease (NAFLD) and type 2 diabetes." (PMID 39125318, 2024). "Notably, metformin, an insulin‐sensitizing drug used as first‐line treatment for type 2 diabetes mellitus (T2DM), improves Nrf2 and KLF2 expression." (PMID 39092773, 2024). "Therefore, assessing IR solely through fasting glucose and insulin measurements may not capture all individuals at risk of developing type 2 diabetes and cardiovascular diseases." (PMID 38792408, 2024). "Research shows that dysbiosis, or alterations in the gut microbiota, can contribute to the development of type 2 diabetes (T2DM) by affecting glucose metabolism, insulin sensitivity, and inflammation." (PMID 39458444, 2024). "Type 2 diabetes (T2DM) is characterized by elevated blood sugar levels, primarily due to impaired β-cell function, leading to inadequate insulin secretion or reduced insulin sensitivity." (PMID 39372950, 2024). "An adolescent presenting with a few months’ duration of polyuria, polydipsia, and weight loss with non-ketotic hyperglycemia and not requiring insulin therapy at diagnosis could be misdiagnosed as having type 2 diabetes or maturity-onset diabetes of the young (MODY)." (PMID 39329041, 2024). "Type 2 diabetes mellitus (T2DM) is a heterogeneous disease that consists of hyperglycemia, insulin resistance, and relative impairment in insulin secretion." (PMID 39597722, 2024). "Type 2 diabetes mellitus (T2DM) is a chronic metabolic ailment that derives from insulin resistance and compromised insulin secretion, perpetuating chronic hyperglycemia." (PMID 38612466, 2024). "Besides weight control, liver fibrosis benefits from enhanced insulin sensitivity and reduced glyco- and lipo-toxicity, which is also the aim of the therapy in Type 2 Diabetes Mellitus (T2DM), owing to the glucose-lowering action of anti-diabetic drugs." (PMID 38668314, 2024).
type 2 diabetes (continued). "The association between type 2 diabetes and CRC may be mainly explained by the stimulating effects of insulin (as an important growth factor) on colonic tumor cells, suggesting that pharmacological or lifestyle interventions that lower circulating insulin levels may be beneficial in preventing CRC." (PMID 38672612, 2024). "The findings of this study indicated that SK supplementation (500 mg per day) can improve glycemic indices (FBS, HbA1C, and Fasting Insulin) and lipid profiles (total cholesterol, LDL-c, and HDL-c) of type 2 diabetes patients." (PMID 38778308, 2024). "Here we performed a chemical screen and identified AZD7762, a compound that potentiates glucose-stimulated insulin secretion (GSIS) of a human β cell line, healthy and type 2 diabetic (T2D) human islets and primary cynomolgus macaque islets." (PMID 37945898, 2024). "Diabetes, particularly Type 2 Diabetes (T2DM), results from insulin secretion and resistance issues, affecting adipose tissue, liver, and skeletal muscle." (PMID 39296128, 2024). "Both plasma insulin concentrations and ISR were elevated post meal in the type 2 diabetes and Obese-NGT groups, compared with Lean-NGT." (PMID 39138690, 2024). "Most within the type 2 diabetes cohort were treated with MDI, while a small proportion were treated with basal insulin or oral agents only." (PMID 38951212, 2024). "Since increased ROS levels are involved in lipolysis of adipocytes and often correlate with type 2 diabetes progression in patients, the effects of PST on the oxidative distress and chronic insulin induced lipogenesis were also investigated in this study." (PMID 38397817, 2024). "These liver changes may reduce hepatic insulin clearance and increase peripheral insulin levels (see further below paragraphs Hepatic Insulin clearance and hyperinsulinemia and The personal fat threshold hypothesis and the development of type 2 diabetes for more details)." (PMID 38791525, 2024). "Our study demonstrated a significant association between S-CPR index and TIR in Japanese patients with type 2 diabetes, demonstrating for the first time that TIR increases with preserved insulin secretory capacity." (PMID 38839813, 2024). "Sulfonylurea drugs, widely used to treat type 2 diabetes, bypass metabolism and close the KATP channel directly, thus stimulating insulin release in both neonatal and type 2 diabetes." (PMID 38366195, 2024). "Early insulin therapy is capable to achieve glycemic control and restore β-cell function in newly diagnosed type 2 diabetes (T2D), but its effect on cardiovascular outcomes in these patients remains unclear." (PMID 38844816, 2024). "In fact, LanDis attempts to encapsulate all available information about diseases—for example, the references of type 2 Diabetes (NIDDM) include information about several clinical trials and multi-year studies on the effects of glucose on insulin levels." (PMID 38200084, 2024). "Compared with Lean-NGT, insulin extraction (Rdins AUC240), defined as the average amount of secreted insulin removed per min, was ~40% and ~62% greater in the Obese-NGT and type 2 diabetes groups, respectively." (PMID 39138690, 2024). "Experimental studies in people with type 2 diabetes that have acutely substituted sitting time with LPA have reported improvements in incremental AUC (iAUC) of glucose, triacylglycerol levels, insulin and insulin sensitivity." (PMID 38656371, 2024). "Due to the critical role of GSK-3 in insulin signaling and GS metabolism, GSK-3 has emerged as a very promising therapeutic target for the treatment of type 2 diabetes." (PMID 39655056, 2024). "mesatlantica significantly reduced the effects of type 2 diabetes, including the decrease of HbA1c and HOMA-IR and the increase of HOMA-β and plasma insulin." (PMID 38926327, 2024). "On the other hand, type 2 diabetes (T2DM) is characterized by insulin resistance and decreased insulin secretion." (PMID 38601207, 2024).